TNF (tumor necrosis factor)
Diseases named in the same sentence as TNF in open-access papers (continued):
Sharing a sentence is not in itself a finding about the gene and the disease.
infection (continued). "A549 cells, either treated with TNFα or infected with CHIKV, were analysed by immunofluorescence using antibodies to p65 to assess NF-κB activation and nsP3 to detect CHIKV infection at either 8 or 24 h post treatment (hpt) or infection (hpi)." (PMID 40006946, 2025). "Cytokine storms induced by factors such as interleukins, tumor necrosis factor, and inducible nitric oxide synthase contribute to systemic vasodilation and the progression to distributive shock, even in the absence of overt infection." (PMID 39859085, 2025). "The expression levels of TNF-α, IL-1β, IP-10 and MIP-1α cytokines were analyzed in the WT, RvΔ0687 and C-Rv0687 strains in the cell-free post-infected supernatants of infected BMDMs at 1–5 days post-infection." (PMID 39063103, 2024). "Moreover, Flot2CD4 mice had increased TNF-α+IFN-γ+IL-2+ multifunctional CD4+ T cells, which play a crucial role in infection control." (PMID 39499901, 2024). "In our hands, infection of BMDMs with Leishmania did not lead to the production of proinflammatory cytokines such as IL-1ꞵ and TNF-α." (PMID 39696675, 2024). "Unlike TNF-alpha, which is usually undetectable on day 10 post-intravenous infection in our mouse model, IL-6 levels remain measurable in the later phase of the disease." (PMID 39204252, 2024). "In the case of BMMΦ, the infection with T. cruzi and stimulation with TNF-α + IFN-γ diminished NO2 protein presence, and interestingly, the infection with the QRO isolate diminished NOS2 protein presence to a major extent as compared to the infection with the CI2 isolate." (PMID 39452749, 2024). "Lastly, other pro-inflammatory cytokines, such as TNF-α, IL-6, IL-8, and IL-9, exhibited significant upregulation at 1dpi compared to controls, and with no further induction at later time points post infection." (PMID 38459109, 2024). "We established that LysM Cre+Ifnarflox/flox mice died by cytokine storm induced by DV1-5P7Sp infection or DV3P12/08P4Bm; however, actual protection by anti-TNF-α Ab seemed to be due to prolonging the survival period until mice produced enough levels of neutralizing antibodies." (PMID 38550855, 2024). "After infection with Streptococcus pneumoniae (S. pneumoniae), ATF3 regulates GPB5 or forms a complex with JUN, thus promoting the production of inflammatory cytokines (TNF-α, IL-1β, IL-6, and IFN-γ)." (PMID 38255898, 2024). "Specifically, TNFα, IL-1β, IL-6, IL-10, and type I interferons (IFN-β) decreased early during infection in all three regimes of mice immunization with rVSV-HTNV-GP." (PMID 38341504, 2024). "TLR4 involvement during the infection was also observed through mediating IL6 and TNFα." (PMID 39729468, 2024). "A transcriptome analysis of IPEC-J2 cells infected with PEDV found that the expression of IFN-α, IFN-β, TNF-α, IL-6, IL-8, and IL-12 was increased 12 h after infection, while their levels were not significantly affected during the early stage of infection." (PMID 39728983, 2024). "During the acute phase of infection, which lasts for a few weeks after transmission, HIV triggers a cytokine storm characterized by the upregulation of several cytokines and chemokines, including IFN-I, IL-15, IL-6, TNF-α, IL-8, IL-18, and IFN-γ." (PMID 39062562, 2024). "A phagocytosis-independent uptake of Mmm by macrophages occurred at a high multiplicity of infection, also found to induce the production of TNF, and both responses were unaffected by non-bactericidal doses of bovine complement." (PMID 38935768, 2024). "However, it is known that host genetics also play a crucial role in the outcome of the infection, particularly through the Th1 response, including the production of IFN-γ and TNF-α." (PMID 39466851, 2024). "In addition, 25–100 mg/kg baicalin attenuated the changes in IL-1β, IL-10, IL-18, TNF-α and IFN-γ mRNA expression compared to that in the infection group (P < 0.01)." (PMID 39075562, 2024).
infection (continued). "By contrast, the overexpression of Ythdc2 could significantly inhibit the expression levels of interferon IFN1, TNF-α, Mx1, ISG15, and Viperin after SCRV infection." (PMID 38361078, 2024). "In terms of the asymptomatic infection model of adult mice by HTNV11, we found that pre-treatment of clophosome promoted the onset of disease, in which mice showed weakened TNFα production with high viral loads." (PMID 38200007, 2024). "Increased bacterial burden in lungs and spleen in the first weeks of infection, with reduced levels of iNOs and TNFα, independent of neutrophil levels." (PMID 39949719, 2024). "Vitamin C may have immunomodulatory functions, such as the suppression of pro-inflammatory cytokines such as interleukin (IL)-6, tumor necrosis factor (TNF)-α, and C-reactive protein (CRP), and reduce oxidative stress, which are increased during infection." (PMID 38730366, 2024). "After 48 h of infection, treatment with TRB did not cause a significant decrease in the TNF-α production, whereas both ML concentrations did when compared with untreated cells and TRB treatment." (PMID 39194287, 2024). "During PRRSV infection, activated alveolar macrophages and other inflammatory cells secrete proinflammatory cytokines such as TNF-α, IL-1α/β, IL-6, IL-8, and IL-12, as well as TGF-β, to recruit neutrophils and lymphocytes to the site of infection and facilitate pathogen clearance." (PMID 38806818, 2024). "Specifically, it happens when an infectious agent-like bacteria enters the bloodstream, immune cells such as macrophages and T cells are activated and release numerous cytokines, including tumor necrosis factor (TNF-α), interleukins (IL-1, IL-6), and interferons (IFN-γ), against infection." (PMID 39593820, 2024). "Therefore, we quantified TNF-α, IL-1β, and IL-6 cytokine levels in PAM culture supernatants that were collected at 24- and 48-h post-infection using commercially available ELISA kits." (PMID 38664855, 2024). "Prior work indicated that TNFα induces cortactin redistribution in ECs to the site of PMN transmigration, with cortactin also involved in pronounced NF-κB activation and IL-8 release upon infection." (PMID 39162263, 2024). "Although older anti-TNF users had numerically higher rates of infections than younger patients, this difference was not specific to biologics, and a similar numeric difference was also noted among those on the placebo." (PMID 39200937, 2024). "Post-infection vaccination did not affect plasma levels of TNF and IL-6, irrespective of the number of doses or PCC status." (PMID 38316833, 2024). "TNF-α and IFN-γ are proinflammatory cytokines primarily produced by activated immune cells, including macrophages, T cells, and natural killer cells, in response to infection, inflammation, or injury." (PMID 38397895, 2024). "Furthermore, the levels of TNF-α and IL-6 in the colonic culture supernatant of JMJD2D-/- mice on day 14 after infection were significantly more than those in the colonic culture supernatants of wild-type mice." (PMID 38905308, 2024). "JN.1 neutralization was similar in patients with versus without breakthrough infection (anti‐TNF, non‐anti‐TNF; each p > 0.05), and neutralization failure was 100% despite breakthrough infection." (PMID 39535484, 2024). "By using a more complex human ex vivo lung model we could further show that the inhibition of STING by H151 decreases cytotoxicity and secretion of IFNα, TNFα and MCP-1 24 h after infection with IAV/PR8." (PMID 39543713, 2024). "The protein levels of TNF-α, MCP-1 and IL-1β upon the treatment with rHtrA for 24 h equalled those of the uninfected controls, whereas the level of IL-8 was significantly decreased by rHtrA infection compared to the control." (PMID 39035711, 2024). "Indeed, compared to HC and IPF patients (which again overall behaved similarly), M-COV1/2 PBMCs secreted, upon infection with live PAO1, less IL-8, MIP-1α, IL-1α, IL-1b, TNF-α, G-CSF, MIP-2α, IL-23 and IL-10." (PMID 38835759, 2024).
infection (continued). "We previously observed significant increases in ileal TNF-α and IL-13 as well as profound differences by network analyses of other host immune factors over time during P. y. yoelii 17XNL infection in basophil-depleted relative to nondepleted mice." (PMID 38780542, 2024). "(B.2.1) Endothelial cells stimulated by IL-37 expression through the secretion of inflammatory mediators, including IL-1β, TNF-α, and IFN-γ, which positively induce adhesion molecules like E-selectin, ICAM-1, VCAM- 1, and VLA-4 that allow immune cells to go to the infection site." (PMID 39308868, 2024). "Our results demonstrate that TNF-α, IL-6, and IL-8 gene expressions, which have been reported to be overexpressed in OSCC, were increased after P. gingivalis and F. nucleatum co-culture infection, demonstrating an augmented cellular response in OKs." (PMID 38612423, 2024). "Once we characterized the cell populations and the phenotype obtained with the stimulation with TNF-α + IFN-γ or IL-4, we proceeded to analyze the effect of the infection of BMMΦ and neonatal mouse cardiomyocytes with two different T. cruzi isolates in the modulation of L-arginine metabolism." (PMID 39452749, 2024). "The TNF-α obtained mean values not higher than 20 ng/mL within 2 h after infection of porcine blood." (PMID 38317258, 2024). "Moreover, the secretion of IL-1β and TNF-α induced by Del4L infection was increased up to about 22 and 4 folds, respectively, higher than that induced by ASFV-WT infection in PAMs." (PMID 38501350, 2024). "In the present study, MXSGD + SJZD may enhance the antiviral effect by modulating the immune response by promoting the expression of Th1 cell-derived TNF-α and IFN-γ and Th2 cell-derived IL-4 at a late stage of FM1 infection." (PMID 39221016, 2024). "In Ps patients, certain drugs, infection, or stress can affect keratinocytes and stimulate the production of pro-inflammatory cytokines, i.e., interferon-α (IFN-α), interferon-γ (IFN-γ), and tumor necrosis factor-α (TNF-α)." (PMID 39124628, 2024). "While TNF influenced chemokine production and leukocyte recruitment to the galea during craniotomy infection, these changes were not destabilizing enough to alter bacterial burden." (PMID 39044282, 2024). "Hence, locally produced pro-inflammatory cytokines such as tumor-necrosis factor alpha (TNFα), interleukins (IL)-1 or IL-6 and prostaglandin E2 could move via systemic circulation to distant organs and contribute to cellular disbalance far away from the side of infection." (PMID 39717783, 2024). "For RSV and IAV coinfection studies in mice, TNF-α and IL-6 were induced during IAV mono-infection." (PMID 38668271, 2024). "We showed a significant increase in NET release to Pseudomonas aeruginosa PAO1 when challenged with inflammatory mediators tumor necrosis factor-α [20 ng mL−1] and interleukin-6 [50 ng mL−1], but not leukotriene B4 [20 nM], compared to the infection alone." (PMID 38189525, 2024). "Several transmembrane proteases, including ADAM17, transmembrane serine protease 2 (TMPRSS), and tumor necrosis factor (TNF)-converting enzyme, along with proteins like vimentin and clathrin are believed to play roles in the comprehensive process of establishing infection." (PMID 38339115, 2024). "The inflammatory cytokines TNFα, IL-4, IL-6, IL-13, IL-10, IL-12 (P40), and IL-12 (P70) along with chemokines including CCL2, CCL3, and CCL5, were significantly elevated in the plasma of c-Flip+/–mice on day 2 post-infection compared that of WT mice." (PMID 39038037, 2024). "Transcripts for c-Myc, Myb, CDK4, TNFα, IFNα, and IFNγ were upregulated during early infection with the virus (3d post-infection) alone but not at 7 days post-infection." (PMID 38279262, 2024).
infection (continued). "Pretreatment of IPEC-J2 cells (on insert membranes) followed by a 2 h infection with ETEC resulted in decreased mRNA levels for IL-1β, TLR5 (P < 0.001), and MyD88 (P < 0.05), but increased mRNA levels for IL-8, TNF-α (P < 0.001), and IL-6 (P < 0.01) compared to the control group of IPEC-J2 cells." (PMID 37875712, 2024). "Furthermore, the gene expression levels of IL-8, TNF-α, and MCP-1 upon infection with T. forsythia ΔhtrA were significantly higher compared to infection with T. forsythia wild-type." (PMID 39035711, 2024). "The qRT-PCR tests of the Tumour Necrosis Factor (TNF) α and IL-10 showed a lower to absent gene expression in all the four types of infection." (PMID 38399810, 2024). "Notably, the levels of TNF-α and IFN-γ decreased in infected mice treated with MelB and administered with GB before infection and those where Mel B and GB were co-administered." (PMID 38620045, 2024). "Myeloid cells produce TNF that triggers apoptosis in either myeloid (autocrine) or non-myeloid cells (paracrine) during infection, and this outcome is completely blocked by vICA-expressing MCMV." (PMID 39772130, 2024). "There was no notable change in lung TNF, IL-12p70 and IL-10 levels at any time point during infection." (PMID 38198478, 2024). "It has been observed that while M. gallisepticum infection alone upregulates pro-inflammatory factors such as TNF-α, IL-1β and IL-6, the presence of M. gallisepticum-derived EVs results in a dose-dependent suppression of these factors in HD11 cells at 24 h post-infection." (PMID 38474071, 2024). "In the kidney, unlike all other tissues examined, TNF-α expression remained unchanged in response to infection." (PMID 39273479, 2024). "While disputed that TNF-α inhibitors significantly increase surgical site infection, this does not exclude an antiresorptive mechanism leading to bony destruction following dental extraction." (PMID 39045331, 2024). "When the piglets were injected with baicalin and probenecid, the IL-1β, IL-10, IL-18, TNF-α and IFN-γ mRNA levels decreased compared to those in the infection group (p < 0.01), which suggested that baicalin and probenecid inhibited cytokine production in piglets infected with G. parasuis." (PMID 39075542, 2024). "Furthermore, we observed a significant increase in TNFα, IL-1α, IL-2, IL-3, IL-4, IL-9, IL-10, IL-12 (P70), IL-17A, and CCL5 on day 4 post-infection in murine macrophages." (PMID 39038037, 2024). "At 72 h post‐infection, these cytokine/chemokine levels shifted with significantly lower IFNγ and IL‐4, significantly higher IL‐5, IL‐10, IL‐17a, and CCL‐5/RANTES, and comparable IL‐2 and TNFα levels." (PMID 37990641, 2024). "During infection with the L. europaeus/GI.1 genotype, we noted a similar increase in the expression level of IL-1β and TNF-α, which was a 3.1-fold change (p = 0.045 for IL-1β and p = 0.004 for TNF-α)." (PMID 39273479, 2024). "Thus, after infection, monocytes from LPD-fed mice had decreased levels of Tnfaip2, whose expression is regulated by TNFα and other proinflammatory stimuli like IL1β and LPS via NFκB activation." (PMID 39349819, 2024). "H. pylori OMVs activate Toll-like receptor (TLR) signaling pathways, resulting in the release of pro-inflammatory cytokines such as interleukin-1β (IL-1β), tumor necrosis factor-alpha (TNF-α), and interleukin-6 (IL-6), which attract immune cells to the infection site." (PMID 39726601, 2024). "STING−/− PM presented decreased levels of IL-6 and TNF-α compared to WT PM after infection with C. perfringens, stimulated or not with HKCA." (PMID 38622656, 2024). "Furthermore, changes in pro-inflammatory cytokines such as TNF-α and IL-6 have been shown to correlate with changes in Cytochromes P450 (CYP) expression and enzymatic activity during infection and inflammation." (PMID 37572137, 2024).
infection (continued). "By contrast, hk-HN trained/restimulated macrophages showed a significantly higher percentage of TNF-α+ cells upon Mtb CDC1551 infection, and a significantly higher percentage of IL-1β + cells after infection with Mtb HN878 or CDC1551, compared to uninfected cells." (PMID 38980014, 2024). "In addition, the TNF-α and CCL2 gene expression levels were significantly higher after infection with the Y. enterocolitica strain 1186C in comparison with the A. caviae strain 1185C." (PMID 38721607, 2024). "Therefore, we employed ELISA to assess the levels of IL-1β, TNF-α, and IFN-α to analyze the different innate immune responses triggered by Del4L or ASFV-WT infection in pigs." (PMID 38501350, 2024). "Upon infection, the EBV dUTPase protein induces the expression of pro-inflammatory cytokines such as IL-6 and IL-1β in microvascular endothelial cells and microglia, as well as TNF-a in astrocytes." (PMID 38248274, 2024). "During C. p infection, the expression of TNF-α and IFN-γ helps the body resist infection." (PMID 38934644, 2024). "For TNF-α, the lowest levels (50 pg/mL) were obtained in the HEV group before infection." (PMID 39796100, 2024). "Collectively, our data demonstrate that IFN-γ priming upregulates TNFR1 expression and sensitize neutrophils to release robust TNF upon infection, while LPS-IFN-γ co-priming promotes RIPK1-dependent pyroptosis by producing sufficient soluble TNF prior to infection." (PMID 38965211, 2024). "In both systems, only TNF-α and IL-6 were substantially increased upon PAO1 infection." (PMID 38470050, 2024). "The protein levels of IFN-γ and IL-6 were significantly increased in the sera on day 3 after MA10 infection, whereas those of TNF-α were not." (PMID 38634132, 2024). "Using small molecule inhibitors designed to inhibit Mip, we demonstrated that treatment of B. pseudomallei-infected murine macrophages with the inhibitor AN_CH_37 resulted in a decrease in secreted pro-inflammatory cytokines IL-1β, TNFα and IL-6, and an increase in MCP-1, 24 hours post-infection." (PMID 38590438, 2024). "Taken together, these findings demonstrate that the co-culture of P. gingivalis and F. nucleatum, rather than the monocultures or the separate infections with the bacteria, increases the expressions of TNF-α, IL-1β, IL-6, and IL-8 in OKs." (PMID 38612423, 2024). "CAS, BRI, and BRI + CAS are affecting the BMDMs tumor necrosis factor-alpha (TNF-α) production but did not change the levels of the anti-inflammatory cytokine IL-10 during C. neoformans BMDM infection." (PMID 38916308, 2024). "Upon infection and mediated by PKC-ζ, SPHK2 is phosphorylated, increasing its nuclear localization and thereby upregulating S1P and increasing histone acetylation and IL-6 and TNFα secretion." (PMID 38474268, 2024). "Also, in immunized horses with an attenuated vaccine, the transcriptome analysis of immune responses in PBMCs after in vitro infection with AHSV revealed the up-regulation of genes of different cytokines such as IL-6, TNF, CXCL2 and IL-1β." (PMID 38396742, 2024). "Glutamate concentrations in the supernatants of U-87 MG human astrocyte cultures were not altered by infection or treatment with TNF before infection, compared with non-infected cells." (PMID 38776344, 2024). "Meanwhile, the expression of innate immune-related genes TNF-α, CCL3, and BAX was upregulated both by infection and fenofibrate at an early stage of incubation (4 h), with higher expression levels with the merge of infection and fenofibrate than by the two conditions separately." (PMID 38543516, 2024). "Interestingly, we observed a decrease in the levels of TNF-α and IL-6 in MNK1−/− cells after 6 h of infection with 2 MOI Vv." (PMID 38980024, 2024). "However, infection by any of these SARS-CoV-2 strains resulted in a mild upregulation of the inflammatory markers including IL-1β, TNF-α, and IL-10 at 3 dpi." (PMID 38257760, 2023).